ALDH2 (aldehyde dehydrogenase 2 family member)
Diseases named in the same sentence as ALDH2 in open-access papers (continued):
Sharing a sentence is not in itself a finding about the gene and the disease.
tumor (continued). "The DC(I + II) NPs were more effective than DC(I) NPs in increasing ROS (9.1 and 4.7 folds) and lipid peroxidation (3.5 and 2.5 folds), as well as depleting GSH (9.3 and 2.51 folds) and ALDH2 activity (81.82% and 56.07%) in tumor tissues of the liver and lung, respectively." (PMID 39076585, 2024). "We next probed the ALDH2 protein level of the tumor and normal tissues of HNSC patients." (PMID 37476181, 2023). "In addition, the tumor-associated gene Activating Transcription Factor 3 (ATF3) was upregulated, and the oncogene Aldehyde Dehydrogenase 2 (ALDH2) was downregulated as the trajectory progressed." (PMID 37745301, 2023). "However, further investigation is needed to understand the mechanisms contributing to the relationship between ALDH2 expressions and B cell infiltration within the tumor immune microenvironment." (PMID 37476181, 2023). "In contrast, ADH1B and ALDH2 were upregulated in the early stage of tumor grade." (PMID 37540213, 2023). "Our analysis on co-expressed genes suggested that ALDH2 may play a role in the tumor immune microenvironment, impacting the response to antitumor agents." (PMID 37476181, 2023). "We also found ALDH2 is involved in regulating the immune response of the tumor microenvironment, and high levels of ALDH2 in bulk HNSC may enhance antitumor immunity, which could improve prognosis." (PMID 37476181, 2023). "ALDH2 decreased as the pathological stage increased, indicating that ALDH2 may serve as a tumor suppressor and inhibit LIHC progression." (PMID 35855852, 2022). "The correlation between ALDH2 expression and immune inhibitors showed an effect for ALDH2 in modifying tumour immunology in HNSC, and there may be a possible mechanism by which ALDH2 regulates the functions of T cells in HNSC." (PMID 35169188, 2022). "It is reported that ALDH2 is involved in tumor drug resistance." (PMID 35477569, 2022). "Our previous study indicated ALDH2 might involve in the tumorigenesis and tumor progression of urological cancers." (PMID 36144737, 2022). "Taken together, ALDH2 plays an important role in the process of tumor resistance." (PMID 35477569, 2022). "The results suggested that the in vivo tumor growth was reduced through ALDH2 upregulation." (PMID 35646120, 2022). "However, there are fewer studies investigating how ALDH2 can directly influence the development and progression of tumor." (PMID 35477569, 2022). "Thus, tumor with low expression of ALDH2 cannot convert retinol to retinoic acid, resulting tumor progression." (PMID 35178443, 2022). "In addition, the correlation between immune inhibitors and ALDH2 expression suggested that ALDH2 regulates tumour immunity in HNSC." (PMID 35169188, 2022). "Interestingly, ALDH2 seems to represent a tumor suppressor in multiple cancer entities as it was found to be universally downregulated in a panel of 12 different TCGA cohorts." (PMID 34572930, 2021). "Besides, ALDH2 was closely related to the inhibition and activation of tumor pathways and a variety of potential targeted agents had been discovered in our research." (PMID 35096916, 2021). "The results showed that restoring the expression of ALDH2 could inhibit tumor progression, and the expression of ALDH2 was regulated by hsa-miR-135-3p." (PMID 34670872, 2021). "At the same time, restoring the expression level of ALDH2 in the cell line could reduce the proliferation ability of tumor cells, and in vivo experiments have also verified our findings." (PMID 34670872, 2021). "Interestingly, mice treated with ALDH2 siRNA alone also exhibited significantly retarded tumor progression (p < 0.01, Student's t‐test), and improved overall survival (p < 0.001, Student's t‐test), compared with the control group." (PMID 34026438, 2021). "The distribution of tumor tissue PD-L1 positivity rates was different between the ALDH2 genotypes." (PMID 34022841, 2021).
tumor (continued). "Importantly, the combination of ALDH2 inhibition and PD‐1/PD‐L1 checkpoint inhibitor was shown to enhance the anti‐tumor activity of effector immune cells." (PMID 34026438, 2021). "Moreover, highly expressed ALDH2 was more likely to appear in male tumor patients (T-test: P < 0.05)." (PMID 35096916, 2021). "All these findings hint at a tumor-suppressive function of ALDH2." (PMID 34572930, 2021). "ALDH2*2 may enhance tumor antigen presentation due to aldehyde-induced DNA damage while suppressing peripheral blood T cell counts and T cell activation." (PMID 34022841, 2021). "Based on the expanded correlation analysis results, we found that ACOX1, ALDH2, FUT6, and LRRC19 have a high association with GPX3 and DIO1 in the TCGA database, whether it is only tumor samples or “tumor samples + normal samples”." (PMID 32316597, 2020). "Last, we find that ALDH2 acts as a tumor suppressor by suppressing tumor formation in vivo." (PMID 32850324, 2020). "After adjusted for other confounding factors, ALDH2 “GG” genotype (P = 0.019), microvascular invasion (P < 0.001), macrovascular invasion (P = 0.006), larger tumor size (P = 0.017), and higher AFP (P = 0.003) remained as independent predictors for a shorter time-to-distant metastasis." (PMID 31737110, 2019). "Furthermore, since ALDH2 enzyme only exists as an active form in the mitochondrial matrix, we thus compared the DEs of functional coding genes in mitochondrial matrix to see whether down-regulation of ALDH2 in tumor is independent from other mitochondria matrix associating proteins." (PMID 29426835, 2018). "We further observed that after the tumour cells from the mice were extracted, isolated, purified, and cultured in vitro, significantly more cell apoptosis was induced in the group subjected to dual-target inhibition of Nrf2 and ALDH2 combined with Ara-C treatment." (PMID 40796730, 2025). "Furthermore, additional mechanisms beyond enhanced MAPK/ERK signaling may contribute to the role of ALDH2 in tumor growth and response to targeted therapy." (PMID 40558540, 2025). "It is also noteworthy that the combination of ALDH2 inhibition and anti‐PD‐1 antibody enhances antitumor immunity and tumor eradication, which may serve as a novel strategy to enhance the efficacy of immune checkpoint blockade in CRC patients, especially in those who consumed alcohol." (PMID 36694633, 2023). "Moreover, upregulating the expression of ALDH2 in HCC cells leads to the inhibition of tumor aggressive behavior in vitro and in vivo, largely exerted by modulating the activity of the ALDH2–acetaldehyde–redox–AMPK axis, which is an important autophagy pathway." (PMID 35237626, 2022). "Also, ALDH2 expression was found to be higher in tumor tissues than the adjacent normal tissues." (PMID 34026438, 2021). "However, high ALDH2 metabolic activities have been observed in tumor ECs as well." (PMID 34386529, 2021). "In vivo experiments also showed that ALDH2 expression could suppress tumor formation." (PMID 32850324, 2020). "We demonstrate that ALDH2 downregulation enhances MAPK/ERK activation, promotes tumor growth, and confers resistance to BRAF and MEK inhibitors." (PMID 40558540, 2025). "The interplay between ALDH2 (aldehyde metabolism) and MAPK/ERK (survival signal pathway) suggests a feedback control network, influencing tumor cell proliferation and treatment response." (PMID 40558540, 2025). "Collectively, these findings suggest that ALDH2 downregulation enhances the inflammatory phenotype and drives metabolic reprogramming through the MAPK/ERK signaling pathway, ultimately promoting tumor growth." (PMID 40558540, 2025). "ALDH2, ADH1B, ALDH3A2, DPT, EPHX2, and GATM were down-regulated in the tumor tissues, which is consistent with the expression of hub genes in the GSE3189 and GSE46517 datasets." (PMID 38378847, 2024).
tumor (continued). "Concerning the 8 MRGs expression pattern, 4 genes, namely ACSL1, ALDH2, TP53AIP1, and ME3, were observed to be downregulated in tumor tissues while being upregulated in adjacent-normal tissues." (PMID 38310106, 2024). "To investigate the anti-tumor role of ALDH2 in vivo, we constructed an orthotopic HCC mouse model using Hepa1-6 cells expressing ALDH2 or a control vector." (PMID 38725845, 2024). "In comparison with DC(I) NPs, DC(I + II) nanocomplex demonstrated a significantly higher accumulation rate in tumor tissues, inhibition-dependent cuproptotic activity for mitochondrial enzymes, and depletion of antioxidant indices (GSH and ALDH2)." (PMID 39076585, 2024). "Our findings also revealed that ECHS1 down-regulation and ALDH2 up-regulation contribute to reduced TME heterogeneity, decreased inflammation, and inhibited AGS and SNU-1 tumor cells migration and proliferation." (PMID 39328412, 2024). "Immunohistochemistry (IHC) staining was performed using (i) PD-L1 antibodies to detect PD-L1 expressions; (ii) CD8 and CD4 to detect Tumor Infiltrating Lymphocytes (TILs); and (iii) CD44, LGR5, and ALDH2 to detect stem cell markers." (PMID 36604635, 2023). "ALDH2 is an isoform of aldehyde dehydrogenase (ALDH) and has been used as a tumor stem cell marker gene." (PMID 35013309, 2022). "As we expected, tumor volume was increased significantly when DZN was withdrawn, because ALDH2 expression recovered gradually to make the tumor cells more resistant to PTX." (PMID 35477569, 2022). "However, silencing of ALDH2 could avoid the tumor-suppressive effects of SNHG16 knockdown." (PMID 35646120, 2022). "The results showed that the mRNA expressions of ALDH1A3, ALDH1L2, ALDH2, and ALDH3A2 were obviously related to tumor purity." (PMID 34928471, 2022). "The down-regulation of ALDH2 by JIB04 was further confirmed by western blot and immunochemistry in NCI-H460/PTX tumor tissues." (PMID 35477569, 2022). "ALDH2-overexpressing NSCLC cells exhibited significantly reduced PTX sensitivity and increased biological characteristics of malignancy in vitro and tumor growth and metastasis in vivo." (PMID 35477569, 2022). "Thus, whether ALDH2 mitigates anti-cancer drug efficacy in tumor should be tested." (PMID 34386529, 2021). "Combination of ALDH2 inhibition and PD‐1 blockade, which increases TILs infiltration in tumor and prevents immune evasion, represents a novel strategy to potentiate immunotherapy in CRC patients with ALDH2 overexpression or heavy alcohol drinking history." (PMID 34026438, 2021). "Linear regression analysis indicated that ALDH2 was strongly and positively correlated with PD‐L1 protein expression in the CRC tumor specimens (r = 0.913, p < 0.0001)." (PMID 34026438, 2021). "To explore the molecular mechanisms underlying the ALDH2-mediated attenuation of LUAD metastasis, we probed the relationship between ALDH2 and the EMT genes which are critical for tumor metastasis." (PMID 32850324, 2020). "Except for MAOB and ALDH2, the expression levels of other metabolism-related genes in LUAD was all in the tumor tissues." (PMID 33193873, 2020). "We showed that XRCC1 and ALDH2 mRNA levels are related and that a high XRCC1 mRNA/low ALDH2 mRNA ratio seems to be accompanied by tumour aggressiveness." (PMID 30088263, 2018). "Of these isoforms, ALDH3A1 was found to be the predominant isoform that was expressed in the primary tumor samples, and this expression was at a much higher level than that of ALDH1A1 or ALDH2." (PMID 28881734, 2017). "All seven glucose metabolism-related proteins were downregulated in SBP1 induced-tumor tissue, including GAA, GAPDH, ALDH2, Thioredoxin, ENO3, UGDH and Lumican." (PMID 25974208, 2015). "Further assessment demonstrated that the expression of necroptosis-related genes, including FADD, MLKL, TLR2, PGAM, HMGB1, CXCL 1, TRAF2, and EZH2, was elevated in tumor tissue, while FAS, RIPK1, RIPK3, TLR3, TNFRSF, ALDH2, and NDRG2 were upregulated in normal intestinal tissues." (PMID 40959081, 2025).
tumor (continued). "By knocking out ALDH2 in ALDH2-normal A375 cells, we demonstrated that ALDH2 downregulation enhanced AcAH and ROS production, MAPK/ERK activation, tumor growth, and resistance to targeted therapy, underscoring its clinical relevance and association with poorer patient survival." (PMID 40558540, 2025). "The expression of MAOA, AKR1A1, ALDH9A1, HAAO, and ALDH2 was significantly downregulated in ESCC tumor tissues compared to non-tumor tissues." (PMID 40821701, 2025). "The CPTAC prediction through the UALCAN platform showed markedly lower ALDH2 protein levels in tumorous (n = 108) than those in normal tissues (n = 71, P = 2.04×10-41), and the trend continued regardless of the tumor grade." (PMID 37476181, 2023). "ALDH2 was shown to upregulate PD-L1 expression in CRC cells in vitro and in tumor tissues." (PMID 34572930, 2021). "ALDH2 plays an important regulatory role in HNSCC and the tumor immune response." (PMID 33506058, 2021). "Importantly, inhibition of ALDH2 reduces PD‐L1 protein in CRC cells and promotes tumor‐infiltrating T cells (TILs) infiltration, presumably leading to the significant potentiation of anti‐PD‐1 antibody efficacy in a mouse CT26 CRC model." (PMID 34026438, 2021). "The knockdown of ALDH2 by specific siRNA was found to potentiate the sensitivity of CT26 tumors to anti‐PD‐1 antibody, leading to a dramatically reduction in tumor burden (p < 0.01, Student's t‐test), and improved overall survival compared with anti‐PD‐1 treatment alone (p < 0.05, Student's t‐test)." (PMID 34026438, 2021). "Furthermore, CRC tissues displaying low ALDH2 expression were accompanied by more CD3+‐ and CD8+‐activated T cells infiltrated in the tumor, and vice versa." (PMID 34026438, 2021). "Moreover, ALDH2 impacts metastasis largely through modulating the ALDH2-acetaldehyde -redox-AMP-activated protein kinase (AMPK) axis, because AMPK modulates lipid metabolism to regulate tumor cell growth and survival." (PMID 32140062, 2020). "Additional studies have reported that ALDH1A1, ALDH7A1, ALDH2 and/or ALDH1A2 are responsible for driving Aldefluor® activity in other tumor types, indicating that the ALDH isoform(s) responsible for Aldefluor® activity may be tumor-specific." (PMID 28937653, 2017). "Most of these genes, including ADH1B, ALDH1A1, ADH1C and ALDH2, were significantly down-expressed in ER+ or ER- tumors compared to tumor-adjacent normal tissues, although none showed significant differential expression by alcohol intake in either tissue type." (PMID 28899409, 2017). "Furthermore, ALDH2 expression in tumor cells is significantly and positively correlated with the infiltration of immune cells, including CD4+ T cells, CD8+ T cells, neutrophils, B cells, and macrophages in various tumor types." (PMID 39735553, 2024). "In addition, ALDH2 and ECHS1 may serve as novel tumor markers, providing a foundational basis for inhibiting GC progression." (PMID 39328412, 2024). "Interestingly, when the ALDH2 rs671 genotype was determined in this study it was found that lower ALDH2 expression level in the tumor was independent of the ALDH2*2 genotype." (PMID 35330099, 2022). "Finally, ALDH2 expression did not correlate with the tumor volume; however, it was described as a part of a gene signature that can be used to predict the visibility of PCa on magnetic resonance imaging (MRI) scans and the biochemical recurrence-free survival." (PMID 34572930, 2021). "ALDH2 belongs to the acetaldehyde dehydrogenase family, and its reduction not only induces proliferation and stem cell properties of LUAD cells but also may induce DNA damage, which will promote tumor recurrence, drug resistance, and metastasis, leading to poor prognosis of LUAD." (PMID 36506314, 2022). "Multiple other datasets support these findings, as ALDH2 was downregulated in CRPC samples over primary PCa and also diminished in samples of recurrent PCa over non-recurrent tumor tissues." (PMID 34572930, 2021).
tumor (continued). "Compared with that in the empty vector group, an effect of Ara-C treatment was not obvious in the ALDH2-overexpression group; however, in the CVT-10216 combined with Ara-C group, tumour cell apoptosis was obvious, accompanied by significant tissue vacuolation and cell fragmentation." (PMID 40796730, 2025).